GDF15 (growth differentiation factor 15)
Diseases named in the same sentence as GDF15 in open-access papers (continued):
Sharing a sentence is not in itself a finding about the gene and the disease.
osteoarthritis (10 papers, 2008 to 2025). A noninflammatory degenerative joint disease occurring chiefly in older persons, characterized by degeneration of the articular cartilage, hypertrophy of bone at the margins and changes in the synovial membrane. "Although there is currently no research on the association between GDF15 and MAPK14 in renal disease, a study has demonstrated the presence of the GDF15/MAPK14 axis in osteoarthritis." (PMID 40854626, 2025). "Future research should aim to include larger PTOA cohorts and place greater emphasis on the early stages of osteoarthritis pathogenesis in order to evaluate the prognostic potential of GDF‐15." (PMID 41287825, 2025). "Drug-targeted MR analyses have further confirmed that metformin targets AMP-activated protein kinase (AMPK) and growth differentiation factor 15 (GDF-15) have genetically predicted protective effects against osteoarthritis." (PMID 39172202, 2024). "GDF15 is a gene with a role not only in bone remodelling, but has also been related to osteoarthritis in humans." (PMID 24498183, 2014). "Research on osteoarthritis (OA) has revealed that the expression of growth differentiation factor 15 (GDF15) may trigger cellular senescence in cartilage cells by activating MAPK14." (PMID 41170318, 2025). "Proteins such as SOX11, FGF23, KLF6, WWOX and GDF15 not implicated previously in the genesis of osteoarthritis were identified." (PMID 19011694, 2008). "To prove our hypothesis that GDF‐15 is differentially expressed in IOA and PTOA patients, we analyzed clinical serum and synovial fluid samples derived from the Ulm Osteoarthritis study cohort." (PMID 41287825, 2025). "In addition we detected novel proteins that were deregulated in osteoarthritis, such as SOX11, FGF23, KLF6, WWOX and GDF15." (PMID 19011694, 2008).
beta thalassemia (9 papers, 2010 to 2026). Beta-thalassemia (BT) is characterized by deficiency (Beta+) or absence (Beta0) of synthesis of the beta globin chains of hemoglobin (Hb). "Newly diagnosed beta‐thalassemia (βT) major showed GDF15 values up to six times higher than healthy controls, while βT intermedia and βT minor also demonstrated increased GDF15." (PMID 40019842, 2025). "Four studies evaluated GDF15 levels in patients with alpha‐ or beta‐thalassemia and all found elevated GDF15 compared to controls." (PMID 40019842, 2025). "Women with beta-thalassaemia who have chronically high levels of GDF15, who consequently develop reduced sensitivity to GDF15, report lower levels of NVP despite their comparatively higher levels of GDF15 in pregnancy." (PMID 39015511, 2024). "Increased apoptosis during the later stages of beta-KD differentiation, as well as a significant increase in GDF15 expression represent characteristic features of ineffective erythropoiesis identified in human beta-thalassemia." (PMID 23861885, 2013). "In patients with beta-thalassemia, the association between CIMT and GDF-15 levels was significant." (PMID 41597417, 2026). "So it was proposed that TWSG1 might act with GDF15 to dysregulate iron homeostasis in beta-thalassemia." (PMID 20827391, 2010). "Thus, it remains unclear whether GDF-15 in healthy individuals correlates only with age ≥ 65 years and whether the correlations with beta-thalassaemia are influenced by patient condition." (PMID 38396781, 2024). "Recent work has shown a correlation of GDF-15 with age in different age and condition groups: those with moderate CVD aged 18–80 years and those with beta-thalassaemia aged 21–32 years." (PMID 38396781, 2024). "GDF‐15, a member of the TGF super family, was elevated in beta‐thalassemia and contributes to hepcidin suppression this is consistent with our study, as it was higher in cases by median of 1839.89 pg/ml than in controls (median of 256.14 pg/ml) of highly statistically significant value (p < 0.001)." (PMID 35846052, 2022).
metastatic disease (9 papers, 2011 to 2025). "Metastatic disease was characterized by higher circulating GDF‐15 levels compared to less advanced stages, in line with the reported data." (PMID 31463975, 2019). "Thus any effect that MIC-1/GDF15 has on local tumor biology, particularly tumor spread is likely to impact most cancer patients, raising the prospect that modulation of MIC-1/GDF15 actions during therapy might reduce the risk of metastatic disease and other complications of cancer." (PMID 25695521, 2015). "Therefore, GDF-15 or GFRAL inhibitors should be evaluated in patients with non-metastatic disease to improve their prognosis." (PMID 41294666, 2025).
systemic sclerosis (9 papers, 2020 to 2025). A chronic disorder, possibly autoimmune, marked by excessive production of collagen which results in hardening and thickening of body tissues. "In patients with systemic sclerosis, growth differentiation factor 15 (GDF-15) is associated with the diffuse subtype of the disease and its related complications." (PMID 40362179, 2025). "Additionally, raised serum GDF15 levels are associated with several renal pathological features and systemic sclerosis, a disease for which one of the hallmarks is fibrosis." (PMID 38132468, 2023). "Among them, only GDF-15 (p < 0.001) and MR-proANP (p < 0.05) levels were found to be statistically higher in patients with systemic sclerosis compared to controls; more data emerged from a detailed analysis of heart biomarkers." (PMID 40362179, 2025). "In our study, GDF15 levels were significantly higher in patients with systemic sclerosis compared to healthy controls and also varied significantly between disease subtypes, consistent with previous reports." (PMID 40362179, 2025). "Considering the variations in disease duration and patient characteristics between our study and those previously published, it is crucial to determine the appropriate stage of systemic sclerosis during which GDF-15 should be assessed." (PMID 40362179, 2025). "GDF-15 has been proposed as a potential biomarker in several chronic respiratory disorders, including COPD5, IPF6, and ILD associated with systemic sclerosis, particularly those cases with lung fibrosis." (PMID 38195721, 2024). "As a severe complication of systemic sclerosis, PAH is characterized by a high incidence and mortality rate, and GDF15 is significantly elevated in the remodelled pulmonary arteries and serum of systemic sclerosis-PAH patients." (PMID 37093513, 2024). "Furthermore, this study confirmed the role of GDF15 as a predictor for systemic sclerosis-related interstitial lung disease and elevated pulmonary artery pressure." (PMID 40362179, 2025). "Additionally, in patients with Systemic Sclerosis, serum GDF15 levels are correlate with disease activity, ILD, and declining lung function." (PMID 38195721, 2024). "GDF-15 serum levels were elevated in Egyptian systemic sclerosis patients, and it could be a treatment target." (PMID 33201838, 2020). "GDF-15 was directly involved in the production of proinflammatory cytokines and chemokines, such as IL-6 and CCL2 in bleomycin-induced mice and systemic sclerosis (SSc) patients with lung involvement." (PMID 35784345, 2022).
adenoma (8 papers, 2011 to 2022). A neoplasm arising from the epithelium. "In comparison with co‐cultured colon epithelial cells with senescent fibroblasts with intact GDF15 expression, cell proliferation, migration, and invasion abilities were repressed in both the adenoma and CRC cell lines." (PMID 31389184, 2019). "In this study, we provide both correlative and functional evidence that senescent fibroblasts and an essential SASP factor, GDF15, induce physiological and molecular changes that promote the adenoma–carcinoma initiation and progression sequence in the colon." (PMID 31389184, 2019). "We found GDF15 expression is elevated in the normal colon from patients with advanced adenomas or CRC." (PMID 31389184, 2019). "In addition, GDF15 levels correlate with tumor progression through the adenoma—carcinoma sequence in colorectal tumors and are elevated in metastatic cancer relative to local disease." (PMID 32310257, 2020). "Similarly, in the Apcmin/+ model of intestinal neoplasia, where mice develop spontaneous intestinal adenomas, mice harboring a copy of the GDF15 transgene exhibited a reduction in the number of adenomas." (PMID 32310257, 2020). "Our data showing elevated senescent cells and GDF15 in the colons of individuals with advanced adenomas or CRC suggest that the accumulation of senescent cells is an in vivo phenomenon in the colon that may mediate increased CRC risk." (PMID 31389184, 2019). "In aggregate, these data provide evidence that the SASP and GDF15 play a role in creating a pro‐oncogenic microenvironment in the colon and may facilitate adenomatous polyp formation and the adenoma‐to‐carcinoma progression sequence." (PMID 31389184, 2019). "These senescent fibroblasts could promote proliferation of epithelial cells in vitro via secretion of Growth Differentiation Factor 15 (GDF15), thereby possibly contributing to adenoma formation." (PMID 33430285, 2021). "We found GDF15 was more highly expressed in subjects with advanced adenomas or CRC compared to subjects with no adenomas or cancer." (PMID 31389184, 2019). "In light of our studies showing GDF15 is a mediator of oncogenic effects of the colon SASP in vitro, we next assessed GDF15 expression in primary human colon mucosa of subjects with no adenomas or CRC, with advanced adenomas, and with CRC." (PMID 31389184, 2019).
Impaired glucose tolerance (8 papers, 2016 to 2025). An abnormal resistance to glucose, i.e., a reduction in the ability to maintain glucose levels in the blood stream within normal limits following oral or intravenous administration of glucose. "GDF15-deficient mice show increased food intake and body weight, and impaired glucose tolerance." (PMID 40443802, 2025). "GDF-15 levels were significantly elevated in subjects with impaired glucose tolerance compared to the subjects with normal glucose tolerance (897.93 [691.57–1616.10] versus 770.36 pg/mL [535.34–1040.0], p = 0.026)." (PMID 27642607, 2016). "Our aim here is to investigate serum hepcidin and GDF-15 concentrations and their associations with each other in nonanemic subjects with impaired glucose tolerance and compare them with the nonanemic subjects with normal glucose tolerance." (PMID 27642607, 2016). "In the present study, we demonstrated that serum GDF-15 concentrations are increased in nonanemic subjects with impaired glucose tolerance compared to subjects with normal glucose tolerance." (PMID 27642607, 2016).
leukemia (8 papers, 2016 to 2025). A malignant (clonal) hematologic disorder, involving hematopoietic stem cells and characterized by the presence of primitive or atypical myeloid or lymphoid cells in the bone marrow and the blood. "In AML models, leukemia-derived GDF15 and stromal-derived TGF-β have been shown to co-activate the PI3K/AKT signaling pathway in adipocytes." (PMID 41279338, 2025). "Our previous studies have demonstrated that GDF15 was highly expressed in leukemia-activated fibroblasts, suggesting that GDF15 was from many kinds of cells in BM of AML patients." (PMID 29566722, 2018). "GDF15 is present both on the membrane and in the cytoplasm of leukemic cells, suggesting that leukemia cells have an autocrine function, which is consistent with the results of ELISA analysis of the leukemia cell lines in vitro." (PMID 27643489, 2016). "Both the CAFs and the leukemia cells secreted GDF15, suggesting that GDF15 plays a critical role in the local cross-regulation between the leukemia cells and the CAFs within the BM in primary AML patients." (PMID 27643489, 2016). "Finally, CAFs influence chemotherapy resistance in certain leukemias by acting on the cell cycle, with growth differentiation factor 15 (GDF15) blocking the cell cycle in the G0/G1 phase, thus limiting chemotherapy sensitivity." (PMID 39765634, 2024). "Meanwhile, leukemia cells contribute to the protective niche formation by secreting chemotactic factors and growth factors, in particular, growth differentiation factor 15 (GDF15)." (PMID 27643489, 2016). "And these functional cells affected the chemosensitivity of the leukemia cells by producing GDF15." (PMID 27643489, 2016). "We propose that CAFs within the BM of AML could also counter the chemo-sensitivity of leukemia cells by producing GDF15." (PMID 27643489, 2016). "From the point of bone marrow microenvironment, GDF15 might be a new target to treat the leukemia." (PMID 29566722, 2018). "Therefore, we guessed that GDF15 secreted by leukemic cells might play an important role in the conversion from adipocytes to leukemia-activated fibroblasts." (PMID 29566722, 2018). "In addition, iron overload has an impact on leukemia transformation and survival, and is known to be related to GDF-11, GDF-15, and hepcidin." (PMID 32344823, 2020). "Indeed, this cascade resulted in the release of several cytokines, like growth differentiation factor 15 (GDF15), CCL3 and CCL4, which facilitated bone-marrow niche reconstruction, offering a protective environment for the remaining leukemia cells post-chemotherapy." (PMID 40565309, 2025).
prostate tumors (8 papers, 2015 to 2022). "Prostate cancer risk estimates, however, suggest that NF‐κB and GDF‐15 expression exert opposite effects on prostate tumor development." (PMID 33784024, 2021). "For example, immunohistochemical staining of prostatectomy specimens showed an inverse association between GDF-15 levels and prostatic inflammation, a known prostate tumor-promoting factor." (PMID 31539407, 2019). "Therefore, although positively correlated in benign prostatic biopsies, NF‐κB and GDF‐15 expression appear to exert opposite effects on risk of prostate tumor development." (PMID 33784024, 2021). "Data from prostate cancer immunohistochemical analyses indicate that NF‐κB and GDF‐15 are overexpressed in prostate tumor as compared to benign adjacent and normal prostatic tissues and overexpressed in bone metastasis specimens from patients." (PMID 33784024, 2021). "In summary, NF‐κB and GDF‐15 expression appear to exert opposite effects on prostate tumor development, especially in AA men." (PMID 33784024, 2021). "Consistent with the survival study above, these data indicate that protection from prostate tumor growth in GDF15 overexpressing TRAMP mice requires intact adaptive immunity." (PMID 32502202, 2020). "GDF15 overexpressing MIC-1fms mice again had significantly smaller prostate tumors than WT mice (p = 0.05)." (PMID 32502202, 2020). "TRAMP mice bearing a germline deletion of GDF15 develop larger prostatic tumors than TRAMP mice with wild-type GDF15." (PMID 31539407, 2019). "Albeit GDF15 expression is downregulated in metastatic CRPCs compared to primary tumors, we found that the levels of GDF15 RNA and protein are higher in primary prostate tumors than in benign prostate tissues." (PMID 31539407, 2019). "On average TRAMPMIC-/- mice died about 5 weeks earlier and had larger prostatic tumors compared with TRAMP mice that were wild type for MIC-1/GDF15 (TRAMPMIC+/+)." (PMID 25695521, 2015). "Since our analysis of benign biopsies shows a lower GDF‐15 expression in AA men, this implies an even greater upregulation from benign glands to intraprostatic tumor (pathologic stage 2) to extra‐prostatic tumor (higher stages), in which GDF‐15 is highest in AA men." (PMID 33784024, 2021). "Much like the suspected diverse role of GDF‐15 in prostate carcinogenesis, NF‐κB may exert differing effects along the continuum of prostate tumor development." (PMID 33784024, 2021). "This tumor localized GDF15 may be important because prostate tumors from patients with early cancer and with increased staining for tumor associated GDF15 have a significantly better prognosis." (PMID 32502202, 2020). "Although this study did not differentiate the nuclear and cytoplasmic staining of MIC-1/GDF15 and NF-κB, we observed a significantly higher nuclear MIC-1 protein in prostate tumors of African American men compared to Caucasians, while the cytoplasmic MIC-1 protein remained similar in both races." (PMID 33081054, 2020). "To directly assess the impact of lack of adaptive immunity on our previously observed GDF15 mediated reduction in PCa growth, we compared prostate tumor growth in a cohort of TRAMP (n = 22), TRAMPfmsmic-1 (n = 15), TRAMPrag-/- (n = 18) and TRAMPfmsmic/rag1-/- (n = 14) mice." (PMID 32502202, 2020). "In order to determine whether GDF15 overexpression altered the lymphocyte composition of tumors, using the OTTEM model, we orthotopically engrafted both WT and MIC-1fms mice with cells derived from prostate tumors of TRAMPMIC-/- mice." (PMID 32502202, 2020). "A tissue microarray-based immunostaining of prostate tumors showed a stage-wise decrease in MIC-1/GDF15 expression in African American men, but there was no change in MIC-1/GDF15 expression by higher grade." (PMID 33081054, 2020).
Atrophy (7 papers, 2015 to 2025). Any weakening or degeneration, especially through lack of use. "The present findings extend previous work by demonstrating that a DNAm GDF15 score is associated with accelerated brain volume loss over time, including in regions vulnerable to atrophy (e.g., SPARE‐AD) in the context of neurodegenerative disease." (PMID 41274863, 2025). "Furthermore, systemic inflammation and elevated serum TNF-α levels were implicated in various pathologies involving muscle atrophy, and GDF-15 was reported to be induced by inflammatory cytokines such as TNF-α." (PMID 38515869, 2024). "We hypothesised that increased circulating and muscle growth and differentiation factor-15 (GDF-15) causes atrophy in ICUAW by changing expression of key microRNAs." (PMID 25516419, 2015). "Recently, another stress-induced cytokine, growth and differentiation factor-15 (GDF-15), a member of the transforming growth factor beta super family, was identified as a mediator of muscle atrophy during critical illness." (PMID 26242743, 2015). "In both cohorts, patients with atrophy had higher serum GDF‐15 than patients without atrophy." (PMID 27239406, 2016).
breast tumors (7 papers, 2014 to 2023). "In this study, we also showed a positive correlation between GDF15 and visfatin expression in breast tumors." (PMID 31861872, 2019). "In human breast tumors, IMP1 mRNA could be post-transcriptional regulated and its expression seemed to be correlated with the reduced levels of its associated transcripts, such as PTGS2, GDF15 and IGF-2 mRNAs." (PMID 26910917, 2016). "We have previously demonstrated direct tumor-promoting effects of visfatin on breast tumor cells mediated via c-Abl and STAT3, and indirect effects via ADSC intermediaries acting via a GDF15-pAKT pathway." (PMID 33256011, 2020). "Correlation of increased IMP1 expression with the reduced levels of its bound mRNAs, such as PTGS2, GDF15 and IGF-2 transcripts, was also observed in human breast tumors." (PMID 26910917, 2016). "Since the P values for IGF2 mRNA was not significant (P > 0.1), the results suggested a positive connection between increased levels of IMP1 and reduced expression of GDF15 and PTGS2 mRNAs in human breast tumors." (PMID 26910917, 2016). "They emphasize that GDF-15 expression was substantially correlated with hepcidin levels in patient samples, both at the mRNA and protein levels, indicating a function for GDF-15 in controlling hepcidin in breast tumors." (PMID 36895478, 2023). "In addition, higher IMP1 protein levels correlated with lower expression of GDF15, PTGS2 and IGF2 mRNAs in human breast tumors." (PMID 26910917, 2016).